INS (insulin)
Diseases named in the same sentence as INS in open-access papers (continued):
Sharing a sentence is not in itself a finding about the gene and the disease.
diabetes (continued). "The reduced first-phase insulin secretion had an important implication on diabetes; it generally represented exhaustion of β cells from a prolonged period of compensation for insulin resistance." (PMID 33920473, 2021). "We used insulin therapy as an indicator of diabetes severity in the present analyses, as has been done previously." (PMID 33648518, 2021). "Although patients with type 1 diabetes were the first to benefit from the discovery of insulin, in 1936, Sir Harold Himsworth suggested that diabetes can be classified into insulin-sensitive and insulin-insensitive types." (PMID 34717951, 2021). "One patient admitted, ‘my real fear of diabetes is if I get so bad that I have to start taking the insulin’." (PMID 33949058, 2021). "Although a variety of oral hypoglycemic drugs that enhance insulin sensitivity have protective effects in reducing AD, insulin used to treat diabetes promoted the occurrence and development of AD." (PMID 35187097, 2021). "The German/Austrian DPV registry includes 3657 patients with diabetes using the tubeless insulin management system." (PMID 33684335, 2021). "It has been proven that the intracellular content of serotonin correlates positively with the insulin secretion rate, and TPH1-deficient mice showed the development of a mild form of diabetes as a result of impaired insulin secretion in the pancreas." (PMID 34772352, 2021). "Diabetes mellitus (DM) is defined as a chronic metabolic disease, characterised by high blood glucose levels resulting from defects in insulin secretion and/or action." (PMID 34158120, 2021). "The purpose of this study is to explore functional health literacy (FHL) and numeracy skills in an insulin-treated, type 2 diabetes mellitus (T2DM) patient population, and their impact on diabetes self-care activities." (PMID 33561956, 2021). "At present, the therapeutic drugs for diabetes, such as insulin and other hypoglycemic agents can only relieve the symptoms of hyperglycemia, and there are certain side effects in the process of treatment." (PMID 34319254, 2021). "Logistic regression models adjusted for age, sex, diabetes duration, treated by insulin, treated by OHA, physical activity, smoking status, alcohol intake." (PMID 34579047, 2021). "Insulin is a 51-residue hormone that is important for the control of glucose metabolism and diabetes treatment." (PMID 33767265, 2021). "Our study population was very young, and it represented an advantage, because all metabolic problems related to the insufficient pancreatic insulin production and diabetes onset were reduced." (PMID 34357331, 2021). "In fact, rescued beta-cell functionality after transplantation allowed an increase in insulin bioavailability, playing a central role in favoring diabetes regression." (PMID 33800465, 2021). "Diabetes specialists choose insulin as the initial therapy to prevent acute exacerbation of glycemic control." (PMID 33502325, 2021). "Pancreatic β-cell dysfunction and insulin resistance in insulin target tissues such as the liver, skeletal muscle and adipose tissues are the two main characteristics of type 2 diabetes mellitus." (PMID 33807522, 2021). "Compared with Caucasians, Asian subjects with normal glucose tolerance (NGT), pre-diabetes or diabetes all had lower insulin secretion post 75-g glucose challenge." (PMID 34917033, 2021). "Despite the great progress made in insulin preparation and titration, many patients with diabetes are still experiencing dangerous fluctuations in their blood glucose levels." (PMID 33921274, 2021). "Eleven patients (61%) had overt pre-operative diabetes mellitus, eight requiring subcutaneous insulin and three required oral anti-hyperglycemic medication and seven had pre-diabetes." (PMID 34169341, 2021). "In this study, we systematically investigated the anti-DR effect of BBR in insulin-treated diabetes." (PMID 34803500, 2021).
diabetes (continued). "These metabolites reduce adiposity, increase energy expenditure and improve glucose and insulin homeostasis in mouse models of obesity and diabetes." (PMID 33772024, 2021). "These miRNAs are highly expressed in insulin-sensitive tissues and are upregulated in rodent models of obesity or diabetes." (PMID 33938394, 2021). "Nevertheless, of these limitations, KDs have been demonstrated to grant a clear beneficial impact on body composition and glucose/insulin homeostasis for obese and/or type 2 diabetes mellitus patients." (PMID 34444726, 2021). "This study also showed that the BMI ≥ 35 kg/m2 group were younger but already had diabetes for an average of 11 years, had higher insulin requirements and were more likely to have additional medications or doses added to their regimen during consultation." (PMID 33757476, 2021). "For example, elevated hGH levels in the bloodstream inhibit insulin action, leading to insulin resistance and diabetes." (PMID 33774052, 2021). "Although many pharmacological interventions are available for managing diabetes such as insulin therapy and oral hypoglycemic agent, an alarmingly increasing trend in incidents of undesirable complications among diabetic patients is currently evident." (PMID 33598184, 2021). "For purposes of this review, we focus solely on the arterial wall vasa vasorum and its role in normal physiology and in pathological transformation of vessels in insulin resistant states such as diabetes, pre-diabetes, and metabolic syndrome." (PMID 34299190, 2021). "Recent research suggests that impaired gap junction coupling is associated with disruptions to glucose homeostasis, altered islet function, and impaired plasma insulin oscillations, similar to that observed in models of diabetes." (PMID 34359828, 2021). "A population-specific equation is suggested based on the current sample, which includes traditional variables explaining differences in RMR such as SMM and FM (which represent weight, and specific variables for diabetes such as the use of insulin and HbA1c)." (PMID 33921537, 2021). "Out of Cushing’s disease patients with type 2 diabetes mellitus, 14 had been receiving metformin, 5 metformin and insulin, and 1 insulin." (PMID 34659130, 2021). "Individuals with higher AD PRS are less likely to start insulin treatment within the first year of diagnosis of diabetes." (PMID 34301914, 2021). "Frequent mutations in metabolism-related genes, especially insulin- and diabetes-related pathways in this study, suggest a potential pathologic role of these genes in GIST and a possible association between GIST and diabetes mellitus." (PMID 34805171, 2021). "Type 1 diabetes mellitus is an autoimmune disease characterised by the destruction of pancreatic β-cells which produce insulin." (PMID 33440853, 2021). "The availability of only one type of medicine at the district hospital and PHC level makes people with diabetes to buy other medication (including insulin) for diabetes at highly unaffordable price." (PMID 34187461, 2021). "At the age of 7.5 months, Wfs1 KO rats showed the first signs of diabetes by reduced c-peptide and insulin, and increased glucagon secretion (p < 0.01)." (PMID 34831417, 2021). "Only those with more severe beta cell decompensation require exogenous insulin to manage their diabetes, and so insulin treatment becomes a de facto marker for endogenous insulin deficiency in the face of the insulin resistance in type 2 diabetes." (PMID 34912295, 2021). "In insulin-treated patients with type 2 diabetes mellitus (T2DM), glycemic control is usually suboptimal." (PMID 33602190, 2021). "Diabetes mellitus is characterized by chronic hyperglycemia resulting from defects in insulin secretion, insulin action, or both." (PMID 34007967, 2021).
diabetes (continued). "Insulin resistance refers to a condition where the pancreas produces insulin, while muscle, liver, and other cells fail to respond to insulin, which leads to glucose intolerance and eventually diabetes, which is the most important link between ATD and CVDs." (PMID 34552566, 2021). "Patients were predominantly female, African American, multi-morbid (with an average of 13 other chronic conditions aside from diabetes), and all but three used insulin to treat diabetes prior to admission." (PMID 34001014, 2021). "Diabetes is a complex metabolic disorder characterized by chronic hyperglycemia resulting from defects in insulin secretion, action or both." (PMID 33855206, 2021). "Nowadays, several diabetes types were well-known, the type-1 diabetes (T1D) resulting from a defect in insulin secretion (accounted by 5–10% of those with diabetes) and the type-2 diabetes (T2D) resulting from a defect in insulin action (90–95%)." (PMID 34574159, 2021). "Several recent clinical and experimental studies have demonstrated the important role of insulin in maintaining myocardial resistance to ischaemia–reperfusion, especially in the presence of diabetes mellitus or insulin resistance." (PMID 34903800, 2021). "The MiniMed 670G is the first hybrid closed-loop (HCL) insulin delivery system for use in diabetes care since 2017 and uses an algorithm to adjust basal insulin delivery automatically every 5 min based on SG values." (PMID 33044604, 2021). "Diabetes: Adults ≥18 years with a random blood glucose ≥200 mg/dl and/or currently on diabetes medication or insulin." (PMID 33777712, 2021). "Women randomised to metformin versus insulin for treatment of diabetes in pregnancy had a significantly lower likelihood of experiencing hypoglycaemia." (PMID 33927270, 2021). "Deterioration of beta-cell function which is thought to be irreversible after 10 years of diabetes, and decreased insulin secretion due to hypoxia-induced acute and chronic de-differentiation of beta-cells, contribute to worsening glycaemic control over time." (PMID 34260650, 2021). "Interviews with pharmacists and diabetes educators reveal that these emotions trigger a certain uneasiness injecting insulin in the presence of others." (PMID 33848301, 2021). "The explanation for the increased concentration of AGEs in patients with diabetes is that higher HbA1c will disrupt normal glucose metabolism in the muscle and fat cells, leading to insulin-mediated glucose uptake and the circulating process of hyperglycemia." (PMID 35370932, 2021). "Participants also had a low frequency of correct responses on the diabetes definition due to insufficient insulin production (7.7%) and the index suitable for awareness about diabetes control in past months (19.3%)." (PMID 33579243, 2021). "In the pathophysiology of diabetes, insulin, the hormone that is produced in pancreatic ß-cells, is essential." (PMID 34804472, 2021). "In type 2 diabetes, individuals develop peripheral insulin resistance prior to clinically evident diabetes, increasing the workload of β cells to increase insulin secretion, leading to a rise in fasting plasma insulin levels (hyperinsulinaemia)." (PMID 34680372, 2021). "These traits are usually accompanied with reduced GLU uptake into the INS-sensitive tissues (e.g., skeletal muscle, liver, and adipose tissue) and are signs of metabolic syndrome/INS resistance that can lead to diabetes and atherosclerosis." (PMID 33744871, 2021). "Further exploration will be needed to examine diabetes management in 2020, particularly among patients with type 1 diabetes, and to assess for changes in insulin use and adherence, glycemic control, and diabetes-related mortality." (PMID 34468753, 2021). "Type 2 diabetes mellitus (T2DM), which is predominantly due to insulin resistance (IR) and deficiency in insulin secretion, accounts for more than 90% of diabetes." (PMID 34603198, 2021).
diabetes (continued). "This study aims to explore the insulin requirement profiles, and analyze the related factors of type-2 diabetes mellitus (T2DM) with different C-peptide levels on insulin pump therapy." (PMID 33483468, 2021). "Diabetes is defined as a heterogeneous metabolic disorder that is characterized by high blood glucose resulting from either impaired insulin sensitivity, secretion, or both." (PMID 33803134, 2021). "Transgenic mice expressing very high levels of Myc in β-cells (estimated in the 20- to 50-fold range) display increased β-cell proliferation and apoptosis, downregulation of insulin gene expression, and development of diabetes." (PMID 33239359, 2021). "Epidemiological studies have shown that patients with type 2 diabetes mellitus (T2DM2) are at increased risk for developing PD, indicating a possible insulin-modulating role in this latter condition." (PMID 34383800, 2021). "The year 2021 marks a momentous milestone for the diabetes community, with the centenary of the discovery of insulin." (PMID 33483763, 2021). "The daily demands of diabetes self-care, including frequent daily blood sugar measurement, multiple injections/boluses, monitoring carbohydrates and exercise to adjust insulin dose have been described as a 24/7 job." (PMID 35356383, 2021). "Pre-injection skin disinfection is thus very important in patients with diabetes who self-inject insulin." (PMID 33418557, 2021). "Diabetes-inducing agents such as STZ selectively obliterates insulin-producing cells in the pancreas while maintaining the remaining functionality of the organ." (PMID 34834340, 2021). "For example, there was a significant difference in glucose-stimulated insulin secretion between an early and advanced stage of diabetes." (PMID 34206641, 2021). "Insulin degludec (IDeg), a novel ultra-long-acting basal insulin, has been extensively tested in a comprehensive study involving a wide range of diabetes patients." (PMID 34876671, 2021). "These microvascular effects of insulin are impaired in insulin-resistance, diabetes mellitus, obesity and hypertension, all common comorbidities in INOCA patients." (PMID 34660730, 2021). "Whilst the majority of these patients will have type 2 diabetes (T2DM), up to 30% or more of patients with diabetes require insulin to help control HbA1c levels." (PMID 34676266, 2021). "In animal studies, injection of bone marrow-derived mesenchymal stem cells (MSCs) improved the insulin sensitivity of a rodent model of diabetes mellitus." (PMID 33661932, 2021). "A total of 100,650 insulin-using people with diabetes were identified in the Aetna administrative claims database and met study criteria, including 11,826 (11.7%) with T1DM and 88,824 (88.3%) with T2DM." (PMID 34238287, 2021). "Viral illnesses can be more difficult to manage in individuals with diabetes due to increased insulin resistance and ketone production." (PMID 34268455, 2021). "Metformin is a drug used to treat diabetes, as it increases the effects of insulin through suppression of gluconeogenesis and glycogenolysis in the liver, and the stimulation of insulin signaling and glucose transport into muscles." (PMID 33923452, 2021). "The sister of the proband (II-2) was first diagnosed with diabetes and diabetic ketoacidosis at 4 years old and was then on insulin therapy." (PMID 34123975, 2021). "This study underlines that the timing of exercise plays a role, at least, in the improvement of the insulin sensitivity in diabetes." (PMID 32737757, 2021). "We have identified immunogenic epitopes from insulin, a prime antigen required for initiation of diabetes in NOD mice, in the crinosomes and the secretome." (PMID 33822842, 2021). "Before the discovery of insulin, diabetes was considered as an incurable disease, and killed tens of millions of people every year, leading to serious complications." (PMID 34383816, 2021). "With the introduction of insulin in 1921, diabetes, then a near uniformly fatal disease, became manageable." (PMID 33845179, 2021).
diabetes (continued). "Meanwhile, a regenerative therapeutic approach of transplanting insulin‐producing cells is being studied in patients with rapidly progressive severe diabetes." (PMID 33759360, 2021). "Diabetes mellitus (DM) is a category of metabolic disorders characterized by hyperglycemia, which occurs when the pancreas stops producing enough insulin or when the body cannot use it." (PMID 34741064, 2021). "As we continue to further delineate the role of insulin signaling in the brain, we hope that this will eventually lead us toward new therapies for obesity, diabetes, and neurodegenerative diseases." (PMID 33845179, 2021). "Approximately one-third (82/270, 30.4%) were taking insulin, the mean duration of diabetes was 12.5 (SD 8.6) years, and the mean HbA1c level at baseline was 7.1 (SD 1.3)." (PMID 34032578, 2021). "This study aims to determine the association between AD and IR in patients from King Abdulaziz Medical City, Jeddah (KAMC-J) and to study the relation between AD and diabetes mellitus treated with insulin." (PMID 34956794, 2021). "In contrast, for inpatients with diabetes and severe COVID-19 the initial indications were to withdrawing ongoing treatments and initiating insulin therapy." (PMID 33648564, 2021). "Basal insulin requirements at diagnosis and after the first year of the disease were greater in those who had acidosis at the onset of diabetes." (PMID 34727899, 2021). "This review focuses on the efficacy of intranasal insulin, its potential benefits, limitations, and role in cognitive improvement in people with diabetes with pre-existing cognitive impairment." (PMID 34540446, 2021). "Third, the stent size, disease duration of diabetes, diabetes control status, and the insulin use or oral anti-diabetes medications were ignored." (PMID 33614333, 2021). "As regards T1DM diagnosis, five articles are consistent with the American Diabetes Association (ADA) criteria and participants had a marked presence of anti-GAD or anti-insulin antibodies." (PMID 34071142, 2021). "Although the clinical indication has yet to be concluded, experimental evidence on deteriorating DR condition in insulin-treated Diabetic Mellitus has been observed in diabetic mice." (PMID 34803500, 2021). "While the main characteristics of type 2 diabetes mellitus are insufficient insulin secretion and insulin resistance, SGLT2 inhibitors have some favorable effects on pancreatic β-cell function and insulin sensitivity." (PMID 33802741, 2021). "Ultimately, this vicious cycle leads to the destruction of insulin-producing beta-cells and clinical manifestation of diabetes mellitus." (PMID 34305937, 2021). "Diabetes impairs the retinal IR signaling pathway and subconjunctival insulin injections restore signaling and normal rates of cell death and protein synthesis." (PMID 33915127, 2021). "It is of great importance to note that subcutaneously injection of mouse FGF1 or intracerebroventricular injection of human FGF1 can significantly improve the insulin sensitivity and reduce the serum glucose levels in mouse models of diabetes." (PMID 35011683, 2021). "The increased mTOR activity is related to insulin resistance, and short-term treatment with rapamycin can lead to an increase of insulin sensitivity, thus ameliorating diabetic mellitus." (PMID 33691762, 2021). "Increased frequency of diabetes has also been observed in iron overload disorders (haemochromatosis and β-thalassemia), attributed to insulin resistance and destruction of pancreatic β-cells." (PMID 34836234, 2021). "For example, the positive association with chlorocyclohexane and chlorobenzene degradation that was observed with diabetes, insulin and hypoglycemic drugs, antihypertensives, and metabolic syndrome was also observed with HbA1c." (PMID 34915914, 2021). "For that, logistic and ordinal logistic regression models were next repeated with the addition of the terms for diabetes and for the interaction between each insulin signaling measure and diabetes." (PMID 33858515, 2021).